ENSG00000273088 (novel protein)
Gene: Protein-coding gene on chromosome 1 (155,169,409 to 155,187,272, reverse strand). Ensembl gene ENSG00000273088.
Genetic constraint (gnomAD): Loss-of-function variants: 17 observed, 20.01 expected, observed/expected ratio (o/e) 0.85, 90% interval 0.58 to 1.27. Missense variants: 237 observed, 251.49 expected, observed/expected ratio (o/e) 0.94, 90% interval 0.85 to 1.05. Synonymous variants: 99 observed, 99 expected, observed/expected ratio (o/e) 1, 90% interval 0.85 to 1.18.